LINC00963 (long independently transcribed non-coding RNA 963)
Synonyms: MetaLnc9
Gene: Long non-coding RNA gene on chromosome 9 (129,476,946 to 129,513,769, forward strand). Ensembl gene ENSG00000204054.
Diseases named in the same sentence as LINC00963 in open-access papers:
LINC00963 is named in the same sentence as 34 diseases in open-access papers, as found by Europe PMC text mining. Sharing a sentence is not in itself a finding about the gene and the disease. The quoted sentences say what the papers report.
prostate carcinoma (11 papers, 2016 to 2025). A carcinoma that arises from epithelial cells of the prostate gland. "Moreover, the LINC00963/miR-542-3p/NOP2 axis could act as an inducer of prostate cancer metastasis and have a diagnostic and therapeutic potential for these patients." (PMID 34334108, 2021). "LINC00963 participates in the progression of several types of cancers, including lung cancer, prostate cancer, and breast cancer." (PMID 38615287, 2024). "In the current study, we further found TRIM24 was positively correlated with Linc00963 in prostate cancer, and was upregulated by Linc00963 in CRPC." (PMID 33643926, 2021). "In the following study, Linc00963 was proved to be a ceRNA in prostate cancer, which further identified the pivotal role of Linc00963 in the metastasis of prostate cancer." (PMID 33643926, 2021). "We found that TRIM24, an established oncogene in CRPC, was positively correlated with Linc00963 in prostate cancer tissues." (PMID 33643926, 2021). "Consistent with our previous study, Linc00963 expression was higher in prostate cancer cells (LNCaP, PC-3, C4-2) than that in RWPE-1 (P< 0.05)." (PMID 33643926, 2021). "For instance, overexpression of LINC00963 in prostate cancer triggered the NOP2-induced EMT pathway by reducing miRNA-542-3p expression, thereby promoting tumor progression." (PMID 34907204, 2021). "LINC00963 could serve as an oncogene by regulating biological processes, including survival, metastasis, and differentiation, was up-regulated in prostate cancer, hepatocellular carcinoma, osteosarcoma, and cutaneous squamous cell carcinoma." (PMID 35774794, 2022). "However, we think these should be other binding miRNAs to link Linc00963 and other oncogenes in prostate cancer." (PMID 33643926, 2021). "TRIM24 mRNA levels were upregulated in prostate cancer cells (LNCaP, PC-3, C4-2) compared with those in RWPE-1 (P< 0.05); these were inversely associated with miR-655 expression and positively associated with Linc00963 expression in prostate cancer." (PMID 33643926, 2021). "Recently, LINC00963, a novel lncRNA, has been reported to be involved in the development of several tumors, such as breast cancer, ovarian tumors, esophageal tumors, cutaneous carcinoma, melanoma, hepatocellular carcinoma and prostate cancer." (PMID 33012724, 2020). "Recently, LINC00963, a newly discovered lncRNA, has been reported to be involved in the development of several tumors, such as breast cancer, ovarian tumors, esophageal tumors, cutaneous carcinoma, melanoma, hepatocellular carcinoma and prostate cancer." (PMID 33012724, 2020). "LINC00963 facilitated NOP2 by sponging the cancer inhibitor miR-542-3p to promote prostate cancer metastasis, where NOP2 promoted prostate cancer invasion by activating the epithelial–mesenchymal transition (EMT) pathway." (PMID 41462962, 2025). "Previous studies have shown that both long intergenic non-coding RNA 00963 (Linc00963) and tripartite motif containing 24 (TRIM24) are activators of the PI3K/AKT pathway, and both are involved in the carcinogenesis and progression of prostate cancer." (PMID 33643926, 2021). "A recently study identified Linc00963 could function as a ceRNA to upregulate NOP2 expression and promote cancer metastasis by sponging miR-542-3p in prostate cancer." (PMID 33643926, 2021). "Importantly, the expression of Linc00963 was further enhanced in CRPC cells (PC-3, C4-2) compared with that in primary prostate cancer cells (LNCaP) (P < 0.05)." (PMID 33643926, 2021). "Recently study found Linc00963 could function as a ceRNA to upregulate nucleolar protein homolog 2 (NOP2) expression and promote cancer metastasis by sponging microRNA (miR)-542-3p in prostate cancer." (PMID 33643926, 2021).
breast carcinoma (8 papers, 2020 to 2025). "For example, LINC00963 has been found to be upregulated in breast cancer tissues and correlated with aggressive tumor characteristics." (PMID 38505593, 2024). "Knockdown of LINC00963 has been shown to enhance DNA damage and oxidative stress, making breast cancer cells more sensitive to radiation." (PMID 38505593, 2024). "LINC00963 has been reported to play oncogenic roles in several cancer types including osteosarcoma and breast cancer." (PMID 34112145, 2021). "Studies have shown that LINC00963 is up-regulated in some cancers, such as breast cancer and liver cancer, and plays a promoting role in cancer progression." (PMID 34112145, 2021). "The oncogenic activity of LINC00963 has been confirmed in some cancers, such as osteosarcoma, breast cancer and ovarian cancer." (PMID 34112145, 2021). "It has been shown that LINC00963 promoted carcinogenesis and radioresistance in breast cancer as LINC00963 was able to antagonize the repressive activity of miR-324-3p on activated CDC42 kinase 1 expression." (PMID 32357409, 2020). "One of the previous studies has shown that knockdown of LINC00963 sensitized breast cancer cells to radiation via the induction of DNA damage and oxidative stress." (PMID 32357409, 2020). "Silencing LINC00963 expression has been shown to inhibit breast cancer progression." (PMID 40303981, 2025). "Consequently, LINC00963 may serve as a promising therapeutic target for breast cancer therapy." (PMID 40303981, 2025). "It has been shown that LINC00963 functioned as a competitive endogenous RNA for miR-214-5p/RAB14 in esophageal cancer, miR-625/ HMGA1 or miR-324-3p/ ACK1 axises in breast cancer." (PMID 32357409, 2020).
hepatocellular carcinoma (5 papers, 2016 to 2022). A malignant tumor that arises from hepatocytes. "Interestingly, a newly published article also found Linc00963 was up-regulated in hepatocellular carcinoma and activated PI3K/AKT signaling pathway." (PMID 33643926, 2021).
lung carcinoma (5 papers, 2020 to 2024). "To map the location of LINC00963, we applied FISH and detected cytoplasmic expression of LINC00396 both in LUAD tissues as well as in lung cancer cells." (PMID 36604626, 2023). "For example, upregulation of LINC00963 can inhibit ubiquitination of PGK1 to activate the AKT/mTOR pathway, thus promoting the metastasis of lung cancer, and DLX6-AS1 promotes tumor proliferation by regulating the JAK/STAT pathway." (PMID 33981850, 2021).
colorectal cancer (4 papers, 2016 to 2022). A primary or metastatic malignant neoplasm that affects the colon or rectum. "However, functional details of LINC00963 in colorectal cancer (CRC) remain to be elucidated." (PMID 34498706, 2021). "Zheng and Zhang reported that LINC00963 was increased remarkably in colorectal cancer (CRC) tissues, and knockdown of LINC00963 inhibits the progression of CRC by promoting the expression of miR-124-3p." (PMID 36213440, 2022). "LINC00963 is high-expressed in various carcinomas, but its expression and function in colorectal cancer (CRC) have not been explored." (PMID 33536018, 2021).
osteosarcoma (4 papers, 2021 to 2022). A usually aggressive malignant bone-forming mesenchymal neoplasm, predominantly affecting adolescents and young adults. "Abnormally expressed LINC00963 has carcinogenic effects on cancers such as osteosarcoma, melanoma and prostate cancer." (PMID 33536018, 2021). "Some scholars have examined the mechanism of action of LINC00963 in cancers, and found that LINC00963 relies on miR-204-3p to regulate fibronectin-1 to promote the proliferation and progression of osteosarcoma." (PMID 33536018, 2021).
head and neck carcinoma (3 papers, 2020 to 2021). A carcinoma that arises from the head and neck region. "In addition, LINC00963 knockdown resulted in impaired migration, invasion and colony formation in head and neck carcinomas, as well as decreased levels of ABCG2 and ABCB5, key regulators of multidrug resistance." (PMID 34697403, 2021).
lymph node metastasis (3 papers, 2020 to 2021). "For example, high-expressed LINC00963 is associated with poor prognosis and lymph node metastasis of ovarian cancer." (PMID 33536018, 2021). "Numerous studies have revealed that higher expression of LINC00963 was correlated with lymph node metastasis, TNM stage and shorter overall survival in several cancers, suggesting that LINC00963 may possess oncogenic activities and contribute to tumor progression." (PMID 32357409, 2020).
melanoma (3 papers, 2020 to 2023). A malignant, usually aggressive tumor composed of atypical, neoplastic melanocytes. "According to previous reports, LINC00963 expression is upregulated in melanoma, and it promotes melanoma progression by sponging miR-608 and upregulating nucleus accumbens-associated protein 1 expression." (PMID 34498706, 2021).
cutaneous squamous cell carcinoma (2 papers, 2021 to 2022). "In addition, LINC00963 regulates the progression of cutaneous squamous cell carcinoma through the miR-1193/SOX4 axis." (PMID 33536018, 2021).
gastric cancer (2 papers, 2021 to 2025). A primary or metastatic malignant neoplasm involving the stomach. "This study demonstrates that LINC00963 splice variants are highly expressed to varying extents in the peripheral blood of gastric cancer patients." (PMID 40966274, 2025). "In addition, high LINC00963 expression was found to be associated with poor prognosis and local recurrence in gastric cancer patients, indicating that LINC00963 might be involved in oxaliplatin resistance." (PMID 34697403, 2021). "In this study, it was evident that autophagic inhibition in gastric cancer improved oxaliplatin sensitivity, whereas LINC00963 knockdown induced downregulation of ATG16L1 expression, thereby improving the effects of oxaliplatin." (PMID 34697403, 2021). "According to the GEPIA database, we found that LINC00963 was aberrantly highly expressed in gastric cancer tissues and that LINC00963 expression positively correlated with ATG16L1 expression." (PMID 34697403, 2021). "In conclusion, LINC00963 and miR-4458 are potential biomarkers for predicting the overall survival of gastric cancer patients." (PMID 34697403, 2021). "We found aberrantly high expression of LINC00963 in gastric cancer patients with recurrence, which led to poor prognosis due to local recurrence." (PMID 34697403, 2021). "LINC00963 may promote epithelial-mesenchymal transition (EMT) in gastric cancer (GC) cells by participating in the Wnt/β-catenin signaling pathway, thereby enhancing their invasion and migration abilities." (PMID 40966274, 2025). "Moreover, targeting LINC00963 to inhibit autophagic flux sensitizes gastric cancer cells to oxaliplatin treatment, suggesting that it is a potential novel therapeutic target for improving oxaliplatin sensitivity." (PMID 34697403, 2021). "Therefore, we sought to unravel LINC00963’s role in mediating autophagy and oxaliplatin sensitivity in gastric cancer." (PMID 34697403, 2021). "Moreover, higher LINC00963 and lower miR-4458 levels were recorded in tissues from gastric cancer patients with local recurrence." (PMID 34697403, 2021). "LINC00963 was highly expressed in gastric cancer patients and cell lines." (PMID 34697403, 2021). "In short, we hypothesized that LINC00963 might be involved in promoting oxaliplatin resistance in gastric cancer by inducing autophagy through targeting of ATG16L1; further online bioinformatics tools predicted that LINC00963 regulated ATG16L1 expression by sponging miR-4458." (PMID 34697403, 2021).
non-small cell lung carcinoma (2 papers, 2023). A group of at least three distinct histological types of lung cancer, including non-small cell squamous cell carcinoma, adenocarcinoma, and large cell carcinoma. "The only non-ceRNA mechanism identified for LINC00963 was from a study, where one group reported that by activating AKT/mTOR pathway and CREB-mediated transcription, LINC00963 drived the malignant progression of non-small cell lung cancer." (PMID 36604626, 2023).
autoimmune disease (1 paper, 2025). A disorder resulting from loss of function or tissue destruction of an organ or multiple organs, arising from humoral or cellular immune responses of the individual to their own tissue constituents. "LINC00963, SNHG15, and SNHG3 are lncRNAs that have garnered attention for their roles in cancer and autoimmune disorders." (PMID 39969652, 2025). "Notably, the up-regulation of lncRNAs such as LINC00963, SNHG15, and SNHG3 underscores their significant involvement in inflammatory cascades and highlights their potential utility as biomarkers or therapeutic targets in autoimmune diseases." (PMID 39969652, 2025).
clear cell renal cell carcinoma (1 paper, 2017). "A lncRNA panel including lncRNA-LET, PVT1, PANDAR, PTENP1, and linc00963, were identified to distinguish clear cell renal cell carcinoma from healthy controls." (PMID 29029437, 2017).
colon adenocarcinoma (1 paper, 2021). "StarBase analysis showed that LINC00963 expression was significantly up-regulated in colon adenocarcinoma tissues (P = 2.9e−23), and survival analysis indicated that high-expressed LINC00963 was associated with poor prognosis of patients." (PMID 33536018, 2021).
depression (1 paper, 2021). "LncRNA LINC00963 has been considered an oncogene in many cancers and was upregulated in the depression group in our research." (PMID 34650925, 2021).
diffuse large B-cell lymphoma (1 paper, 2021). "In this present study, we wonder to know the role of LINC00963 in diffuse large B-cell lymphoma and conducted in vivo and in vitro experiments to validate how it involves in the pathomechanism of diffuse large B-cell lymphoma based on bioinformatics analysis." (PMID 34112145, 2021).
metastasis (1 paper, 2021). The spread or migration of cancer cells from one part of the body (where they first appeared) to another. "In the present study, it was observed that LINC00963 expression was upregulated in CRC tissues and cells, which is consistent with a previous study; moreover, the high expression of LINC00963 was associated with larger tumor size and lymph node metastasis in patients." (PMID 34498706, 2021).
metastatic tumors (1 paper, 2023). "Analysis of clinicopathological features of LUAD patients demonstrated that LINC00963 levels were positively correlated with shorter overall survival, and were significantly higher in advanced tumors (TNM stage: III + IV, n = 41) and metastatic tumors (n = 34)." (PMID 36604626, 2023).
oral carcinomas (1 paper, 2020). "To evaluate the effect of LINC00963 on the features of cancer stemness, we utilized the lentiviral-mediated approach to downregulate the expression of LINC00963 in two types of oral cancer cells." (PMID 32357409, 2020). "Altogether, our results showed that suppression of LINC00963 may be beneficial to inhibit chemoresistance and cancer relapse in oral cancer patients." (PMID 32357409, 2020). "Since LINC00963 participated in the aggressiveness in various cancers, it is of great importance to elucidate whether LINC00963 possess the ability to modulate cancer stemness, especially in oral cancer." (PMID 32357409, 2020).
oral squamous cell carcinoma (1 paper, 2020). "In the present study, we assessed the expression of LINC00963 in oral squamous cell carcinoma (OSCC) and examined the contribution of LINC00963 in cancer stemness." (PMID 32357409, 2020).
ZIKV infection (1 paper, 2017). "For example, LINC00963 and LINC00342, anti-apoptotic factors, are downregulated by ZIKV infection." (PMID 29116029, 2017).
cancer (17 papers, 2016 to 2025). A tumor composed of atypical neoplastic, often pleomorphic cells that invade other tissues. "For example, SNHG15 and LINC00963 have been implicated in cancer and other inflammatory conditions, raising concerns about their specificity for RA diagnosis." (PMID 39969652, 2025). "Our research results showed that the LINC00963 alternative splicing was mainly caused by the 59 base increase in the 5’ end of the second exon and the deletion of the third exon, which may be due to the splicing variants produced by different malignant tumors." (PMID 40966274, 2025). "LINC00963 is primarily recognized for regulating immune responses and promoting cancer cell proliferation and migration through mechanisms like sponging miRNAs in ceRNA networks." (PMID 39969652, 2025). "Numerous studies have shown that LINC00963 has an oncogene role in tumor occurrence and development, promoting the metastasis and invasion of cancer cells, which is consistent with our results." (PMID 40966274, 2025). "LINC00963 can activate the oncogenic AKT/mTOR signaling pathway or EGFR signaling pathway to enhance cancer cell metastasis." (PMID 38615287, 2024). "To explore mechanisms underlying the oncogenic activities of LINC00963, we focused on EMT, the biological process critical for cancer metastasis." (PMID 36604626, 2023). "Firstly, RT-qPCR was used to detect LINC00963 expressions in cancer tissues and adjacent tissues of 53 patients with CRC." (PMID 34498706, 2021). "Analysis of TCGA (the Cancer Genome Atlas) datasets suggested that the level of LINC00963 was positively correlated with the expression of the cancer stemness markers (Sox2 and CD44) and drug resistance markers (ABCG2 and ABCB5)." (PMID 32357409, 2020). "Our results demonstrated that the LINC00963-mediated cancer stemness and resistance to chemotherapy were through ABCB5." (PMID 32357409, 2020). "Moreover, the relative expression of LINC00963 was consistently increased in sphere cells, CD44+, and ALDH1+ cells derived from two types of OSCC cell lines (SAS and GNM), suggesting that LINC00963 was also elevated in CSCs and may be associated with the cancer aggressiveness." (PMID 32357409, 2020). "Suppression of LINC00963 effectively reduced the cancer aggressiveness and sensitized chemotherapy through the downregulation of ABCB5." (PMID 32357409, 2020). "Most importantly, we showed that the repressed self-renewal, invasion, and colony-forming capacities after a silence of LINC00963 were all reversed by overexpression of ABCB5, suggesting that LINC00963-mediated cancer stemness was through regulation of ABCB5." (PMID 32357409, 2020). "In summary, we demonstrated that the aberrant upregulation of LINC00963 in OSCC contributed to the cancer stemness." (PMID 32357409, 2020). "The molecular importance of ABCB5 in promoting cancer stemness and chemoresistance is underscored by their findings, which suggest that targeting LINC00963 could sensitize resistant cancer cells and improve therapeutic outcomes in OSCC patients." (PMID 40445912, 2025). "Concurrently, LINC00963 has been proven to involve in cancer progression." (PMID 39252325, 2024). "Interestingly, LINC00963, which stimulates aggressiveness in several cancers, was previously depicted as a potential pluripotency-associated gene in oral CSCs." (PMID 35318304, 2022). "LINC00963 has been reported to be high-expressed in various cancers." (PMID 33536018, 2021). "Therefore, combined with previous studies, we found that LINC00963 was up-regulated in CRC, which was associated with its role as a tumor pro-oncogene in promoting proliferation and growth of cancer cells." (PMID 33536018, 2021). "Furthermore, by performing in vivo experiments, up-regulating and down-regulating LINC00963 expression, we have fully demonstrated that LINC00963 has a cancer-promoting effect on CRC." (PMID 33536018, 2021).